MTOR (mechanistic target of rapamycin kinase)
Diseases named in the same sentence as MTOR in open-access papers (continued):
Sharing a sentence is not in itself a finding about the gene and the disease.
ovarian carcinoma (continued). "In ovarian cancer cells, PI3K/AKT signaling has been demonstrated to affect cell proliferation via FRAP1(mTOR)/P70S6K1-mediated mechanisms." (PMID 20604938, 2010). "Using human ovarian cancer samples, a correlation was observed between the activated status of the VEGFR2 and downstream markers of the AKT/mTOR signalling pathway, pS6 and p4E-BP1 protein." (PMID 19240722, 2009). "In light of the importance of glycolytic induction and mTOR activation in supporting cell proliferation in ovarian cancer, the absence of changes to the activity of the AMPK/mTOR system is surprising." (PMID 40175359, 2025). "In addition, treatment with baicalein increased the expression of DDIT4 (a negative regulator of mTOR), enhanced AMPK phosphorylation, and reduced phosphorylation of downstream effectors S6K1 and S6, consistent with prior studies in breast and ovarian cancer." (PMID 41303544, 2025). "In ovarian cancer, the PI3K/AKT/mTOR pathway is significant for tumorigenesis and progression." (PMID 40647429, 2025). "Cardamonin’s impact on both mTOR and STAT3 pathways emphasizes its role as a potential therapeutic agent that could disrupt TAMs’ support of ovarian cancer, offering a promising avenue for enhancing immunotherapy in this challenging cancer type." (PMID 40330466, 2025). "Notably, treatment with investigational anticancer agents such as AICAR, an AMPK activator, and PI-103, a dual PI3K/mTOR inhibitor, was shown to restore GSTM5 expression and increase treatment sensitivity in resistant ovarian cancer cells." (PMID 40868127, 2025). "Interestingly, inhibition of glutaminolysis by the glutaminase inhibitor CB-839 sensitized ovarian cancer cells to PP242 treatment, the same mTOR inhibitor which also blocked C. parvum infection in this study." (PMID 41156614, 2025). "Pristimerin, another naturally occurring triterpenoid, has been shown to inhibit the proliferative activity of OVCAR-5, MDAH-2774, OVCAR-3, and SK-OV-3 ovarian cancer cells and induce the intrinsic apoptosis pathway by suppression of prosurvival signaling proteins, like p-AKT, p-mTOR, and NF-κB." (PMID 41373772, 2025). "Despite growing evidence that cannabinoids such as CBD and THC can modulate cancer cell proliferation and survival, the molecular basis of these effects in ovarian cancer, particularly in relation to the PI3K/AKT/mTOR pathway and its upstream regulator PTEN, remain largely unexplained." (PMID 41472794, 2025). "Toxin microcystin from Cyanobacteria upregulated the PARP pathway to alleviate NSCLC, and anti-tumor xanthones from Garcinia nujiangensis inhibited the MAPK/ERK and Akt/mTOR signaling pathways and activated the PARP pathway to suppress proliferation and induce apoptosis of ovarian cancers cells." (PMID 40123978, 2025). "For ovarian cancer, metabolic changes such as high insulin and leptin levels may trigger cancer through pathways like PI3K/AKT/mTOR and weaken immune responses." (PMID 41189943, 2025). "Preclinical studies have demonstrated that TCM and its active constituents can inhibit the proliferation of ovarian cancer cells, promote apoptosis, reverse drug resistance, and modulate key oncogenic signaling pathways, including PI3K/Akt/mTOR, Wnt/β-catenin, Notch, NF-κB, and MAPK pathways." (PMID 40406243, 2025). "Additionally, the activation of p-AMPK rescued the promoting effect of XTP8 on EMT in ovarian cancer cell lines, indicating that XTP8 acts as an oncogene by modulating the AKT/AMPK/mTOR pathway." (PMID 38717641, 2024). "In addition, this study revealed that HDAC7 promotes ovarian cancer cell proliferation and invasion by augmenting the phosphorylation of AKT/mTOR and HDAC7 expression is positively correlated with poor prognosis." (PMID 39431349, 2024). "Ovarian cancer, often termed the “silent killer” due to its high mortality rate, shows promising response to SNG in epithelial ovarian cancer cells by controlling the CASC2-EIF4A3 axis, blocking NF-κB signaling, or the PI3K/AKT/mTOR pathway." (PMID 39239653, 2024).
ovarian carcinoma (continued). "Mechanistically, HDAC7 enhanced ovarian cancer progression by activating p‐AKT and p‐mTOR." (PMID 39431349, 2024). "Autophagy death of ovarian cancer cells was induced by up-regulating the expression of autophagy markers Beclin-1, LC3B, and Atg7, down-regulating the expression of P62, and inhibiting the expression of the Akt/mTOR/S6K pathway." (PMID 39464892, 2024). "Additionally, XTP8 enhances ovarian cancer migration, invasion, and EMT via the AKT/AMPK/mTOR signaling pathway." (PMID 38717641, 2024). "The inhibition of PI3K/AKT/mTOR pathway by UBE2S could induce apoptosis and impede the cell cycle, thereby restraining the invasion and proliferation of ovarian cancer cells and correlating with poorer survival prognosis." (PMID 38312603, 2024). "ITGB2 might control mTOR expression via the PI3K-AKT pathway, thus promote mitochondrial glycolysis transformation and cell energy supply in ovarian cancer." (PMID 38345576, 2024). "GALNT14, a member of the acetylgalactosaminyltransferases family, which can regulate the stability of EGFR proteins to inhibit the EGFR/mTOR pathway, has significantly higher levels of GALNT14 in cisplatin resistance ovarian cancer tissue compared to cisplatin sensitive ovarian cancer tissue." (PMID 39192972, 2024). "Particularly in ovarian cancer, several miRNAs (e.g., miR-142-5p, miR-181c, and miR-1271) modulate the sensitivity of tumoural cells to cisplatin and/or paclitaxel-based therapies, mainly through modulation of the PI3K/Akt/mTOR axis." (PMID 39594652, 2024). "Based on this information, we hypothesized that SsnB could suppress estrogen-dependent cell proliferation in breast and ovarian cancer cells and that this effect could develop through the inhibition of the PI3K/AKT/mTOR signaling pathway." (PMID 39770406, 2024). "RNF43 mutations with impaired E3 ligase activity were found in several types of cancers (e.g., gastrointestinal system tumors and endometrial and ovarian cancer), pointing to a high dependency on FZD receptors and possibly PAR2 and the PI3K/AKT/mTOR signaling pathway." (PMID 39125653, 2024). "In addition, combined PI3K/mTOR and ERK inhibition can reverse therapeutic resistance in ovarian cancer cell lines, but the clinical efficacy of these agents requires further preclinical determination." (PMID 38539161, 2024). "To further clarify that HDAC7 promotes ovarian cancer progression via regulating AKT/mTOR signalling, we treated OVCAR‐3 and ES2 cells with MK‐2206 2HCl, an AKT inhibitor and tested the expression pattern of AKT/mTOR‐related proteins such as p‐AKT and p‐mTOR." (PMID 39431349, 2024). "TTK, mTOR, p-mTOR, AKT, p-AKT, 4EBP1, p-4EBP1, Bcl-2 are highly expressed in ovarian cancer, Bax, Caspase3 are lowly expressed in ovarian cancer, and cell apoptosis is inhibited, leading to the deterioration of ovarian cancer." (PMID 36849137, 2023). "In ovarian cancer, the PI3K/MTOR pathway is the most frequently altered." (PMID 37958970, 2023). "Specifically, they observed a significant rise of mTOR levels in endometriosis and endometrioid ovarian carcinoma (EnOC) patient samples, compared to non-affected controls and other ovarian carcinoma histotypes, respectively." (PMID 37627318, 2023). "In addition, HERPUD1 promotes the proliferation of ovarian cancer cells, inhibits apoptosis, affects the cell cycle, promotes the occurrence of autophagy, and inhibits EMT and PI3K/AKT/mTOR and p38MAPK pathways." (PMID 36544104, 2022). "USP13 amplification in human HGSOC may contribute to the development of resistance of PI3K/AKT inhibitors in ovarian cancer, and targeting USP13 may overcome cancer cell resistance against targeted therapy for PI3K/AKT/mTOR pathway." (PMID 35173307, 2022). "Additionally, fibroblast growth factor (FGF), which is also secreted by adipose tissue-derived stromal cells has been shown to induce E-cadherin down regulation via PI3K/Akt/mTOR and MAPK/ERK in OVCAR4 and SKOV3 human ovarian cancer cells." (PMID 35565396, 2022).
ovarian carcinoma (continued). "Considering the role of the Akt/mTOR pathway in DNA damage repair, we hypothesize that RAD21 affects the ovarian cancer cell response to PARP inhibitors not only by mediating sister chromatid cohesion but also by activating the Akt/mTOR pathway." (PMID 35860572, 2022). "Resveratrol, a small polyphenol compound, increases apoptosis induction by activating it in an AMPK-dependent manner, and activates caspase 3, which leads to the inhibited expression and activation of mTOR, a downstream signaling target of AMPK, in ovarian cancer cells." (PMID 35203301, 2022). "In 2019, it was reported that YAP is highly expressed in ovarian cancer, and silencing YAP may significantly inhibit the malignant behavior of ovarian cancer cells by regulating the PI3K/Akt/mTOR pathway." (PMID 35173685, 2022). "The blockade of the AKT/mTOR pathway activated the compensatory MEK/ERK pathway to promote autophagy and apoptosis induced cell death and cell cycle arrest in prostate, cervical and ovarian cancers." (PMID 35860020, 2022). "Previous study found that the down-regulation of NRSF/REST suppresses mTOR signaling in ovarian cancer cells, therefore we asked whether NRSF/REST elevation is related to mTOR activation under HGP exposure." (PMID 35850767, 2022). "Compound 114, which differs from 115 by an additional glycone at the C-28 position, induces apoptosis in a caspase-independent manner via blocking of significant pathways like mammalian target of rapamycin (mTOR) and mitogen-activated protein kinase (MAPK) in human ovarian cancer cells at 94.87 μM." (PMID 34885716, 2021). "In SKOV3 ovarian cancer cells, our data revealed that PAA induced cell apoptosis and autophagy by suppressing the phosphorylation of mTOR and p70s6k protein, which may downregulate the pro-survival signals regulated by the mTOR/p70s6k axis." (PMID 34669780, 2021). "In ovarian cancer cells, bufalin could downregulation of HIF-1α via inhibiting the phosphorylation of mTOR and then inducing the suppression cell growth and migration." (PMID 35004308, 2021). "In ovarian cancer, tanshinone IA significantly suppresses cell proliferation in vitro and tumor growth in vivo by inducing apoptosis and promoting autophagy via the inactivation of the PI3K/AKT/mTOR pathway in ovarian cancer." (PMID 35145409, 2021). "It is speculated that the HEVM/AKT/mTOR/HIF-1α axis and HIF-1α/AKT/mTOR axis may construct a feedback loop to promote ovarian cancer progression, which needs further investigation." (PMID 35004308, 2021). "Although mTOR has been reported as important target for sensitization of ovarian cancer cells for chemotherapy, it has not yet been considered in context of CAM-DR." (PMID 33287446, 2020). "This underscores the concept that simultaneous blockade of multiple cell growth/survival pathways, including JAK/STAT3, PI3K/AKT/mTOR, SRC and MEK/MAPK, may be required to achieve maximum anti-tumor activity in patients with ovarian cancer." (PMID 32927828, 2020). "We showed that LAIR-1 could suppress ovarian cancer cell growth both in vitro and in vivo via the PI3K-Akt-mTOR pathway." (PMID 32628130, 2020). "Therefore, our data suggest that MHY2245 inhibited ovarian cancer cell proliferation and induced autophagy by inhibiting the SIRT1/Akt/mTOR pathway." (PMID 32398958, 2020). "In conclusion, low-concentration metformin treatment of patients with ovarian cancer may have antitumor effects and synergistic effects when used in combination with chemotherapy through the AKT/mTOR pathway." (PMID 32825834, 2020).
ovarian carcinoma (continued). "Concurrent activation of multiple signaling pathways, including JAK/STAT3, PI3K/AKT/mTOR, SRC, and MEK/MAPK, appears to be more common in ovarian cancer and might be the critical force that drives ovarian cancer cells to proliferate and survive." (PMID 32927828, 2020). "The combination of MTOR inhibitors, and EGFR, RTK, PI3K signaling inhibitors might be synergy to inhibit ovarian cancer development." (PMID 32958005, 2020). "In addition, highly expressed JPX shows poor prognosis; promotes the proliferation, invasion, and migration of human ovarian cancer cells, and inhibits cell apoptosis by activating the PI3K/Akt/mTOR signaling." (PMID 31941509, 2020). "Instead, the concurrent activation of multiple signaling pathways, including PI3K/AKT/mTOR, SRC, MEK/MAPK, and JAK/STAT3, appears to be more common in ovarian cancer and may play an important role in ovarian tumor growth." (PMID 32927828, 2020). "Interestingly, a recent study reported that PI3K/AKT/mTOR/NFκB axis is activated by ghrelin, an endogenous ligand for growth hormone secretagogue receptor (GHSR), promoting ovarian cancer cell survival and cisplatin resistance." (PMID 32395722, 2020). "After 24 h of culture in OCM, the phosphorylation of AMPK at Thr172 was reduced and was inversely correlated with the increased phosphorylation of mTOR at Ser2448 and phospho-pP70S6K Thr389 in ES-2 and SKOV3 ovarian cancer cells after culturing in OCM for 24 h." (PMID 31372520, 2019). "Thus, in this study, we also investigated the effect of rfhSP-D on ovarian cancer signaling, using the SKOV3 cell line as an in vitro model- with emphasis to mTOR pathways." (PMID 31338320, 2019). "We found that the PI3K/AKT/mTOR pathway, a downstream signaling pathway of IGF-1, was more strongly activated by the intake of animal protein (casein) than the intake of plant protein (soy protein) in mice with ovarian cancer." (PMID 31284691, 2019). "Furthermore these miRs target WNT signaling, AKT/mTOR signaling and TLR-4/MyD88 to regulate ovarian cancer progression and resistance." (PMID 31608277, 2019). "Stated differently, a diet that was high in plant protein (soy protein) reduced the growth of human ovarian cancer cells in mice in comparison to a diet that was high in animal protein (casein), possibly through the relative inhibition of the IGF/Akt/mTOR pathway." (PMID 31284691, 2019). "Furthermore, to further investigate the inhibition of the Akt/mTOR signalling pathway in Pae-induced autophagy, we rescued Pae-induced Akt/mTOR inhibition by decreasing p-Akt with MK2206 and analysed LC3-II conversion in Pae-treated ovarian cancer cells." (PMID 31406198, 2019). "This indicates the suppression of mTOR signaling is not sufficient to account for the effect of low AMPK in promoting ovarian cancer aggressiveness." (PMID 31372520, 2019). "Low adiponectin levels may favor the aberrant ovarian cancer growth, induced by the persistent activation of PI3K/Akt/mTOR signaling." (PMID 31052147, 2019). "Furthermore, MB induced apoptosis via autophagy through the ROS/AMPK/mTOR pathway, while elevating reactive oxygen species (ROS) together with 5′ AMPK, and reducing mTOR in human ovarian cancer A2780 cells." (PMID 28304343, 2017). "Our previous study in ovarian cancer cells found that either the deprivation of glutamine or the inhibition of glutaminolysis by compound 968 significantly reduced cell proliferation and induced apoptosis through AMPK/mTOR/S6 pathway." (PMID 28969010, 2017). "Contrary to other ovarian cancer cell lines, protein expression of the mTORC2 complex components, mTOR and RICTOR, displayed a modest increase rather than a decrease during mitotic arrest when compared to interphase cells." (PMID 28152500, 2017). "For example, it was demonstrated that inhibition of the PI3K/Akt/mTOR and Ras/MAP signaling pathways could restrict ovarian cancer development by activating autophagy." (PMID 27825125, 2016).
ovarian carcinoma (continued). "The current study shows that simvastatin inhibited the protein expression of phosphorylated p42/44, AKT and S6 in in ovarian cancer cell lines and orthotropic xenografts of serous ovarian cancer, suggesting simvastatin reduced the activity MAPK and AKT/mTOR pathways in ovarian cancer." (PMID 26503475, 2016). "As evidenced in different ovarian cancer cell lines and also in human tissue samples mTOR pathway activation is not an ubiquitous finding in ovarian cancer drug resistance, hence stratification via a biomarker is necessary." (PMID 27090655, 2016). "Therefore, to improve the sensitivity of ovarian cancer cells to platinum-based chemotherapy, targeting the PI3K/ATK/mTOR signal pathway has emerged as one of the major therapeutic strategies." (PMID 26325371, 2015). "Next, we used lentiviral particles carrying mTOR or p70S6K1 cDNAs lacking their 3′-UTR regions to infect miR-497 stable-expressing ovarian cancer cells." (PMID 26238185, 2015). "Meanwhile, ERK pathway activation is critical for baicalein-induced autophagy in ovarian cancer HEY cells instead of Akt/mTOR cascade (data not shown)." (PMID 26549806, 2015). "Increased phosphorylated S6 and phosphorylated p42/44 protein expressions were observed in the three cell lines after treatment with glutamine for 24 h, indicating the positive effects of mTOR/S6 and MAPK signaling pathways on cell proliferation in response to glutamine in ovarian cancer cells." (PMID 26045471, 2015). "The AKT/mTOR and MAPK pathways seem to be major pathways involved in the regulation of cell proliferation, invasion and bioenergetics by glutamine in some cancers including ovarian cancer." (PMID 26045471, 2015). "Additionally, miR-718 represses VEGF and inhibits ovarian cancer cell progression, and mediates Nef- and K1-induced angiogenesis via activation of AKT/mTOR signaling in AIDS-Kaposi's sarcoma." (PMID 25237831, 2014). "However, it is known that PI3K/AKT activation contributes to a reduced response to chemotherapy in ovarian cancer and that modulation of the PI3K/AKT/mTOR pathway is suitable for overcoming resistance to chemotherapy." (PMID 24036443, 2013). "The AKT/mTOR signaling pathway has a major role in cisplatin resistance in ovarian cancer cells; LY294002, the inhibitor of PI3K/mTOR, has been shown to sensitize ovarian cancer cells to cisplatin." (PMID 24137412, 2013). "Finally, FGF2-induced cell invasion was abolished by the inhibition of the PI3K/Akt/mTOR and MAPK/ERK pathways, and the forced expression of E-cadherin diminished the intrinsic invasiveness of ovarian cancer cells as well as the FGF2-induced cell invasion." (PMID 23554977, 2013). "The targeting of multiple signaling pathways such as VEGFR, EGFR, IL-6R-JAK-STAT3/NF-κB, PI3K/AKT/mTOR, and ABC drug transporters in ovarian cancer may be an auspicious start to favourable PFS and OS outcomes." (PMID 22481932, 2012). "Recently, results from our and others studies in HtTA cervical and ovarian cancer cells have demonstrated that RIG1 inhibits expression and activation of signaling molecules such as HER2, RAS, PI3K/AKT and mTOR that are involved in the regulation of cell growth, apoptosis and tumor invasion." (PMID 19245694, 2009). "Furthermore, active mTOR was not significantly different in ovarian carcinoma compared to postmenopausal endometriosis." (PMID 38893278, 2024). "However, the mTOR inhibitor everolimus and bevacizumab in recurrent ovarian cancer patients did not improve response compared to bevacizumab alone." (PMID 39125689, 2024). "The phosphatidylinositol 3-kinase (PI3K)/protein kinase B (AKT)/mammalian target of rapamycin (mTOR) pathway is known to be aberrantly activated both in endometriosis and EAOC; however, its role in the progression of endometriosis to ovarian cancer remains unclear." (PMID 37627318, 2023).